FZD9 (frizzled class receptor 9)
Description:
Receptor for WNT2 that is coupled to the beta-catenin canonical signaling pathway, which leads to the activation of disheveled proteins, inhibition of GSK-3 kinase, nuclear accumulation of beta-catenin and activation of Wnt target genes (By similarity). Plays a role in neuromuscular junction (NMJ) assembly by negatively regulating the clustering of acetylcholine receptors (AChR) through the beta-catenin canonical signaling pathway (By similarity). May play a role in neural progenitor cells (NPCs) viability through the beta-catenin canonical signaling pathway by negatively regulating cell cycle arrest leading to inhibition of neuron apoptotic process. During hippocampal development, regulates neuroblast proliferation and apoptotic cell death. Controls bone formation through non canonical Wnt signaling mediated via ISG15. Positively regulates bone regeneration through non canonical Wnt signaling (By similarity).
Synonyms: CD349; FZD3
Tractability: Antibody: its Gene Ontology location is reachable by antibodies, with high confidence; UniProt places it where antibodies can reach, with medium confidence; UniProt predicts a signal peptide or a membrane-spanning region. PROTAC: UniProt records ubiquitination sites on it; ubiquitination databases record sites on it.
Target class: Frizzled family G protein-coupled receptor; Membrane receptor
Gene: Protein-coding gene on chromosome 7 (73,433,778 to 73,436,120, forward strand). Ensembl gene ENSG00000188763.
Subcellular location: Cell membrane
Pathways (Reactome):
Signal Transduction: Class B/2 (Secretin family receptors)
Gene Ontology:
Molecular function: protein heterodimerization activity; protein homodimerization activity; Wnt-protein binding; Wnt receptor activity; transmembrane signaling receptor activity
Biological process: negative regulation of neuron apoptotic process; positive regulation of neural precursor cell proliferation; regulation of cell cycle; bone regeneration; canonical Wnt signaling pathway; negative regulation of mitochondrial depolarization; negative regulation of mitochondrial outer membrane permeabilization involved in apoptotic signaling pathway; negative regulation of necroptotic process; negative regulation of skeletal muscle acetylcholine-gated channel clustering; nervous system development; non-canonical Wnt signaling pathway; ossification; positive regulation of apoptotic process; positive regulation of bone mineralization; positive regulation of canonical Wnt signaling pathway; regulation of cytosolic calcium ion concentration; regulation of skeletal muscle acetylcholine-gated channel clustering; release of cytochrome c from mitochondria; cell surface receptor signaling pathway
Cellular component: cell surface; cytoplasm; plasma membrane; endoplasmic reticulum membrane; Golgi apparatus; membrane; mitochondrial membrane; filopodium membrane; perinuclear region of cytoplasm
Genetic constraint (gnomAD): Loss-of-function variants: 30 observed, 29.74 expected, observed/expected ratio (o/e) 1.01, 90% interval 0.75 to 1.37. The upper end of that interval is the gene's LOEUF score, 1.37, which puts it in group 5 of 6, group 1 being the genes least tolerant of losing a copy. Missense variants: 822 observed, 763.3 expected, observed/expected ratio (o/e) 1.08, 90% interval 1.02 to 1.14. Synonymous variants: 384 observed, 344.23 expected, observed/expected ratio (o/e) 1.12, 90% interval 1.02 to 1.21.
Homologues: Orthologues: chimpanzee FZD9 (100% identical), macaque FZD9 (99% identical), dog FZD9 (97% identical), pig FZD9 (96% identical), rat Fzd9 (96% identical), mouse Fzd9 (96% identical), guinea pig FZD9 (95% identical), rabbit FZD9 (85% identical), zebrafish fzd9b (72% identical), tropical clawed frog fzd9 (70% identical), zebrafish fzd9a (69% identical), Drosophila melanogaster fz3 (26% identical). Paralogues in human: FZD10 (63% identical), FZD4 (47% identical), FZD8 (42% identical), FZD5 (41% identical), FZD1 (41% identical), FZD2 (40% identical), FZD7 (40% identical), FZD3 (34% identical), FZD6 (31% identical), SMO (25% identical), SFRP4 (16% identical), FRZB (14% identical), and 3 more.
Diseases named in the same sentence as FZD9 in open-access papers:
FZD9 is named in the same sentence as 49 diseases in open-access papers, as found by Europe PMC text mining. Sharing a sentence is not in itself a finding about the gene and the disease. The quoted sentences say what the papers report.
breast carcinoma (10 papers, 2014 to 2026). "This study evaluated FZD9 protein expression in breast tumors and explored its transcriptional modulation in breast cancer cell lines exposed to cytotoxic and epigenetic agents." (PMID 41808318, 2026). "The Wnt/Frizzled signaling pathway is implicated in tumor progression, yet the expression patterns and regulatory dynamics of Frizzled class receptor 9 (FZD9) in breast cancer remain poorly defined." (PMID 41808318, 2026). "The association between FZD9 and NR2E1 immunoreactivity in different clinicopathological parameters in our patient cohort that consists of 80 breast cancer patients." (PMID 33304345, 2020). "As a proof of concept, we confirmed the clinical significance and prognostic value of two of the eight shortlisted genes (NR2E1, FZD9) belonging to this gene signature in our patient cohort consisting of 80 breast cancer patients." (PMID 33304345, 2020). "For example, SPRY4 affects cell growth as a downstream effector of Wnt7A/Fzd9 signaling in ovarian cancer, breast cancer, colorectal cancer and prostate cancer." (PMID 32581828, 2020). "METABRIC analysis of several Wnt signaling targets overexpressed in breast cancer revealed that Wnt2 and Frizzled 9 (Fzd9) were inversely correlated with IGF-1R expression in humans." (PMID 30458886, 2018). "Participation of FZD9 in carcinogenesis has been reported in various cancers, indicating their potential roles in breast cancer, such as mTOR signaling pathway." (PMID 27786176, 2016). "In parallel, breast cancer cell lines were treated with trichostatin A, 5-aza-2'-deoxycytidine, cisplatin, doxorubicin, paclitaxel, and ionizing radiation, followed by quantification of FZD9 mRNA levels by RT-qPCR." (PMID 41808318, 2026). "The results obtained from our IHC panel for both FZD9 and NR2E1 demonstrated the sensitivity of our shortlisted genes in discriminating between basal-like TNBC samples and other breast cancer molecular subtypes." (PMID 33304345, 2020). "Many members of this module, including WIF1, WNT1, SFRP1, FZD9, and FZD8 were hypermethylated and underexpressed in both luminal-A and luminal-B breast cancers but exhibiting larger deviations in DNAm and mRNA expression in the luminal-B subtype." (PMID 26664652, 2015). "For example, Wnt7a and Frizzled-9- (Fzd9-) mediated noncanonical Wnt signaling showed an antitumor activity, but Wnt5a exhibited contradictory effects on breast cancer." (PMID 27895670, 2016).
lung carcinoma (7 papers, 2012 to 2022). "Loss of FZD9 in these cell lines altered expression of lung cancer associated genes and targets of PPARγ, a downstream measure of FZD9 activity." (PMID 35924166, 2022). "FZD9 is rarely mutated in lung cancer, suggesting that dysregulation of FZD9 in the lung epithelium occurs at the transcriptional or translational level." (PMID 35149732, 2022). "If the mouse models parallel the human experience, Fzd9 expression will be lower in cigarette smoke-exposed populations at high risk for lung cancer." (PMID 27339092, 2016). "Previous gene expression screening suggested estrogen receptor expression may be increased by FZD9 loss and alterations in estrogen receptors have been associated with lung cancer, so we measured expression of estrogen receptor α (ESR1) and β (ESR2)." (PMID 35924166, 2022). "Loss of Fzd9 could be an early event in the development of lung cancer, perhaps even in pre-malignant lesions, and might prevent response to iloprost." (PMID 27339092, 2016). "This work improves our understanding of FZD9 regulation in the lung and provides valuable insight for future studies of the mechanisms of iloprost lung cancer chemoprevention." (PMID 35149732, 2022). "We also discovered changes in the expression of new targets of FZD9, including EZH2, IL1β, and VEGFA, all of which are associated with lung cancer." (PMID 35924166, 2022). "FZD9-/- adenomas had significantly higher expression of polo-like kinase 1 (PLK1) and cyclin D1, which are associated with altered cell cycle control in lung cancer." (PMID 35924166, 2022). "We have identified the transmembrane receptor Frizzled 9 (FZD9) as a mediator of the effects of lung cancer chemoprevention with prostacyclin." (PMID 35149732, 2022). "Expression of Frizzled 9 (FZD9) is critical to the activity of the lung cancer chemoprevention agent and prostacyclin analogue, iloprost." (PMID 35149732, 2022). "In NSCLC, FZD9 expression is downregulated in pre-malignant and tumor tissues and induced expression of FZD9 expression inhibits in vitro lung cancer cell colony formation." (PMID 34604862, 2021). "Increased prostacyclin in these models leads to increase or maintenance of Fzd9 expression, supporting a relationship between prostacyclin and Fzd9 expression in the context of lung cancer development." (PMID 27339092, 2016). "Regulation of Fzd9 in the normal lung and during lung cancer progression is poorly understood, so we are interested in exploring mechanisms leading to prostacyclin’s effect on Fzd9." (PMID 27339092, 2016). "If Fzd9 is important in initial stages of cellular dysfunction, then understanding how Fzd9 expression is lost in lung cancer is key to prevention with an agent that signals through Fzd9." (PMID 27339092, 2016). "Targeting miR-520a-5p could be an approach to restoring FZD9 expression and improving response to iloprost lung cancer chemoprevention." (PMID 35149732, 2022). "To determine whether Fzd9 expression changes in human lung cancer, we measured Fzd9 mRNA levels in matched normal and tumor lung tissue." (PMID 27339092, 2016). "Our data would also suggest that identifying pharmacological activators of Wnt7a/Fzd9 pathway and/or hsa-miR29b might have utility in the treatment of lung cancer." (PMID 23862015, 2013). "Mutations in Frizzled receptors are not common in lung cancer and regulation of FZD9 in the lung is largely unknown." (PMID 35924166, 2022). "FZD9 is unique among Frizzled receptors in that it does not activate oncogenic signaling pathways in lung cancer but contributes to maintenance of a normal lung epithelium and exerts tumor suppressive effects when partnered with Wnt7a or iloprost." (PMID 35149732, 2022). "Finally, we also show that hsa-miR29b plays an important role as a tumor suppressor in lung cancer by targeting murine double mutant 2 (MDM2), revealing novel nodes for Wnt7a/Fzd9-mediated regulation of NSCLC cell proliferation." (PMID 23862015, 2013).
lung carcinoma (continued). "However, miRNA that directly target FZD9 have not been described in any context prior to our current study, so this work represents an important step toward understanding regulation of FZD9 in lung cancer." (PMID 35149732, 2022). "Additionally, recent studies have demonstrated that the combined expression of WNT7A and Frizzled 9 (Fzd9) in Non-small cell lung cancer (NSCLC) cell lines inhibits transformed growth by activating ERK5 and increasing PPARgamma activity, representing a novel tumor suppressor pathway in lung cancer." (PMID 22313908, 2012).
Williams-Beuren syndrome (6 papers, 2013 to 2023). "FZD9 is in the chromosomal region 7q11.23 and alterations are associated with Williams-Beuren syndrome, while loss of FZD9 in mouse models has been associated with slight abnormality in B-cell development, impaired osteoblast function, and learning defects." (PMID 35924166, 2022). "Co-expression of FZD9 and Nestin has been observed in neural stem progenitor, derived from patients with Williams syndrome, a developmental disorder caused by mutations in chromosome 7." (PMID 29849507, 2018). "FZD9 is one of the genes, whose homozygous deletion in humans induces Williams-Beuren syndrome, a disorder associated with multiple manifestations, including low bone mass." (PMID 24391920, 2013). "Another BP-associated candidate gene, FZD9, is located in the Williams syndrome (WS) deletion region; WS is a genetic neurodevelopmental disorder characterized by cognitive, behavioral, emotional and social symptoms, which is dependent on the genes involved in the deletion." (PMID 38136791, 2023). "Recurrent breakage at this fragile site has been implicated in the Williams-Beuren syndrome and and this region contains the genes LIMK1, EIF4H(WBSCR1), AUTS2 as well as the tumor suppressor gene FZD9." (PMID 33444353, 2021). "It is suggested that, in humans, FZD9 may be involved in the regulation of bone formation, because its deletion in the Williams-Beuren syndrome, a rare genetic disease with multiple manifestations, is associated with low bone mass." (PMID 24391920, 2013).
hepatocellular carcinoma (5 papers, 2014 to 2023). A malignant tumor that arises from hepatocytes. "Alterations in FZD9 have been associated with cancers including astrocytoma, osteosarcoma, acute myeloid leukemia, and hepatocellular carcinoma." (PMID 35924166, 2022). "FZD9 has been studied in multiple cancers including NSCLC, astrocytoma, osteosarcoma, AML, and hepatocellular carcinoma (HCC)." (PMID 34604862, 2021). "Interest in the role of FZD9 in the lung was initiated by the discovery that FZD9 and Wnt7a induced non-canonical and tumor suppressive signaling in NSCLC cells, in contrast with studies in osteosarcoma and hepatocellular carcinoma." (PMID 35924166, 2022).
astrocytoma (4 papers, 2018 to 2021). "FZD9 is also upregulated in astrocytomas and induces EMT through the canonical WNT/β-catenin/TCF pathway by binding WNT5a." (PMID 34604862, 2021). "Fzd9 is aberrantly expressed in malignant astrocytoma and gastric cancer." (PMID 34836197, 2021). "FZD9 expression was reported to be upregulated in astrocytoma and osteosarcoma." (PMID 29789460, 2018).
glioma (4 papers, 2018 to 2022). A benign or malignant brain and spinal cord tumor that arises from glial cells (astrocytes, oligodendrocytes, ependymal cells). "However, decreased expression of FZD9 was positively associated with the progression of gliomas from grade II to grade IV." (PMID 36699699, 2022).
non-small cell lung carcinoma (4 papers, 2012 to 2024). A group of at least three distinct histological types of lung cancer, including non-small cell squamous cell carcinoma, adenocarcinoma, and large cell carcinoma. "In non-small-cell lung carcinoma, the antitumorigenic effect of Wnt7a interacting with the specific receptor Fzd9 was mainly mediated through ERK-dependent activation of the nuclear receptor gene PPARγ." (PMID 23304155, 2012). "In non-small cell lung cancer, peroxisome proliferator-activated receptor γ (PPARγ), a downstream target of Wnt7A/Fzd9 signaling, inhibits non-small cell lung cancer cell proliferation by up-regulating SPRY4 expression levels through regulating SPRY4 promoter activity." (PMID 38686189, 2024). "miR-31 indirectly affects FZD9 expression to mediate the effects of prostacyclin and CSC exposure in human bronchial epithelial cells (HBEC), non-small cell lung cancer (NSCLC) cell lines, and mice." (PMID 35149732, 2022).
osteosarcoma (4 papers, 2017 to 2022). A usually aggressive malignant bone-forming mesenchymal neoplasm, predominantly affecting adolescents and young adults. "In aggressive osteosarcoma, FZD9 and WNT2 expression are induced by proto-oncogene c-Fos." (PMID 34604862, 2021).
Cognitive impairment (3 papers, 2022 to 2026). Abnormal cognition is characterized by deficits in thinking, reasoning, or remembering. "By increasing the doubling time and apoptosis of nerve cells, the deletion of the FZD9 gene can affect the development of the nervous system and cause cognitive impairment." (PMID 35379245, 2022). "Research has shown that FZD9, as an important factor in neural cell regulation, is highly expressed in the hippocampus, and the deletion of the FZD9 gene could affect the development of the nervous system and cause cognitive impairment by increasing the doubling and apoptosis of nerve cells." (PMID 38136791, 2023).
lung adenocarcinoma (3 papers, 2013 to 2022). A carcinoma that arises from the lung and is characterized by the presence of malignant glandular epithelial cells. "With the current study, we present the first investigation of effects of FZD9 loss in the urethane lung adenocarcinoma model." (PMID 35924166, 2022).
adenoma (2 papers, 2020 to 2022). A neoplasm arising from the epithelium. "Increased COL1a2 may result from the presence of cancer associated fibroblasts in FZD9-/- adenomas and is associated with poor prognosis." (PMID 35924166, 2022). "In this first examination of a FZD9 negative, urethane-induced, lung adenoma cell line, we found that compared to a wildtype urethane-induced adenoma cell line, loss of FZD9 led to increased expression of apoptosis inhibiting, proliferation promoting, and EMT genes." (PMID 35924166, 2022). "We also found changes in protein expression that would lead to suppression of apoptosis in FZD9-/- adenomas." (PMID 35924166, 2022). "Increased BCL2 in FZD9-/- adenomas suggested an effect of FZD9 loss on cell survival, so we measured apoptosis proteins in the WT and FZD9-/- adenoma cell lines by protein dot blot." (PMID 35924166, 2022). "Together, these data suggest that FZD9-/- adenomas have increased capacity for aggressive behavior and have higher levels of factors that promote tumor progression." (PMID 35924166, 2022). "FZD9-/- adenoma cells had increased ability to grow in an anchorage independent environment and to migrate, suggesting a more dedifferentiated phenotype." (PMID 35924166, 2022). "Overexpression of FZD9, a receptor to Wnt proteins, further links adenomas from female patients with EGF, as the EGFR pathway interacts with Wnt/ßcatenin signalling." (PMID 32183012, 2020). "Significantly elevated N-cad, FN1, and VEGF may contribute to increased potential of FZD9-/- adenomas for progression to carcinoma." (PMID 35924166, 2022). "Interestingly, CYP3A5 together with CALB1, DAPL1 and FZD9 were recently reported to be enriched in human ACTH-secreting adenomas compared to other pituitary adenomas." (PMID 32183012, 2020). "In whole lung analysis from mice in this study, active β-catenin was increased with urethane but was not higher in FZD9-/- tissue compared to wild type, suggesting that loss of FZD9 alone in the uninvolved tissue surrounding adenomas does not contribute to increased β-catenin signaling." (PMID 35924166, 2022).
melanoma (2 papers, 2020). A malignant, usually aggressive tumor composed of atypical, neoplastic melanocytes. "The FZD9 transcript showed the highest range (1.10) in primary melanoma samples in relation to metastatic samples." (PMID 32431053, 2020).